PRF1 (perforin 1)
Diseases named in the same sentence as PRF1 in open-access papers (continued):
Sharing a sentence is not in itself a finding about the gene and the disease.
cancer (continued). "Therefore, more studies are needed to clarify the exact mechanism of PRF1’s role in cancer progression in order to better guide the development of relevant therapeutic strategies." (PMID 39199299, 2024). "Based on these findings, PRF1 may be a valuable biomarker both for the treatment of cancer and for its prognosis in the future." (PMID 39199299, 2024). "Our further exploration of the critical gene of ICDRM, PRF1, revealed that it could serve as a stable prognostic marker for many tumors and is significantly differentially expressed across cancer types." (PMID 37291495, 2023). "Hence, we proposed that the overexpression of hsa-miR-3120-5p in MPE decreases PRF1 expression and inhibits the immune response against cancer cells, leading to the formation of MPE." (PMID 36684253, 2022). "In one study quantitating immune cytolytic activity based on the expression level of the CD8 T cell cytolytic effector molecules granzyme A (GZMA) and perforin (PRF1), ccRCC ranked highest among 15 cancer types, and the scoring was markedly increased compared to pRCC and benign renal tissue." (PMID 34831452, 2021). "The core module of cytolytic effector molecules appears largely conserved across murine and human viral, human aging, and human cancer contexts: notably, GZMB+ cytotoxic CD4+ T cells co-express GZMA and often GZMH, PRF1, FGFBP2, and granule-associated proteins NKG7 and (in humans) GNLY." (PMID 34910940, 2021). "Perforin (Prf1) and granzyme B (GzmB) are key cytotoxic effectors that kill cancer cells for NKs." (PMID 33868269, 2021). "Although deficiencies in PRF1 correlate with diminished target cell lysis by effector T lymphocytes and NK cells and increased risk of cancer, the importance of lacking individual GZMs remains elusive." (PMID 32466293, 2020). "However, co-segregation data between cancers and germline variants are needed to definitively assess the role of BLM and PRF1 genes in GC predisposition." (PMID 31514334, 2019). "By estimating the cytotoxic T lymphocyte (CTL) activities through Perforin (encoded by PRF1) and Granzyme B (encoded by GZMB) expression, we observed a negative correlation between RGMB expression levels and CTL activities in 30 of 33 cancer types (p = 2.6 × 10−6, χ2 test)." (PMID 31061392, 2019). "A down-regulation of PRF1 by miR-34a over-expression in CTLs (cytotoxic T cells) may impact the immune response against cancer cells." (PMID 31311583, 2019). "Similarly, Perforin-1 pores are required for the penetration of granzymes to help kill virus-infected and cancer cells." (PMID 27857713, 2016). "Different – but sometimes overlapping and perhaps complementary – strategies are required by the immune system to eliminate extracellular bacteria (complement and poly-C9), intracellular viruses and cancer cells (Perforin-1), and intra- and extracellular bacteria (Perforin-2)." (PMID 27857713, 2016). "Non-silent mutations of BRCA1, PRF1, and other cancer genes were detected solely in the metastasis stage." (PMID 24405831, 2014). "Thus, an extensive analysis of GZMA, GZMB, GZMK and PRF1 may not only provide a greater understanding of their role in cancer biology, but also reveal their similarities and differences across different cancer types." (PMID 40002821, 2025). "In particular, when examining cytotoxic T cells in the different cancers, we observed the highest correlation values for GZMA (correlation coefficient: 0.921), GZMB (correlation coefficient: 0.902) and PRF1 (correlation coefficient: 0.928) in BLCA." (PMID 40002821, 2025). "In contrast, Cycling GZMA CD4 T cells expressed GZMA and demonstrated a marked upregulation of anti-cancer-related genes, including IFNG, PRF1, and TNFSF10." (PMID 40959273, 2025). "A pathway analysis was conducted to evaluate the inhibitory and activating effects of ten cancer-related pathways on the expression of GZMA, GZMB, GZMK and PRF1." (PMID 40002821, 2025).
cancer (continued). "To further characterize the TME, we performed gene expression analysis of tumors from Prf1+/+ and Prf1–/–MMTV-PyMT mice treated with either vehicle or SnMP for 36 hours, using the NanoString nCounter platform with the Pan-Cancer Immune Profiling Panel." (PMID 40627458, 2025). "As a comprehensive pan-cancer exploration, we next investigated the impact of DNA methylation of GZMA, GZMB, GZMK and PRF1 on survival outcomes." (PMID 40002821, 2025). "The cytolytic activity (CYT) score is a new index of cancer immunity calculated from the mRNA expression levels of GZMA and PRF1, representing immune cytotoxicity." (PMID 38438381, 2024). "For example, the top 15 hub genes in T cells from all types of cancers included those involved in cell-mediated immunity (GZMB, PRF1 and IFNG) and immune checkpoint signaling pathways (TIGIT and CTLA4)." (PMID 36350625, 2023). "A third group of cancers comprised of BLCA, BRCA, UCEC, LIHC, STAD, PRAD and THCA showed a similar expression pattern with first group of cancers except for the contrast behavior of NLRP3, NLRC4, PRF1, CASP1, CASP4, and GZMA (downregulated in this group)." (PMID 36605187, 2022). "CD8+ T cells can kill cancer cells by releasing GNLY or GZM and PRF1 and enhance immunotherapy through the PD-1/PD-L1 immunosuppressive axis, helping to break immune tolerance." (PMID 35860239, 2022). "Further analysis revealed a significant decrease in antitumor factors (GZMA, GZMB, NKG7, and PRF1) in CD8T cells and an increase in the proportion of cancer cells, especially in the cancer-cell-dominant group." (PMID 36497182, 2022). "Intriguingly, Flt3L mRNA correlated to the markers of a metagene signature indicative of immunogenic cancer cell death, which encompassed Caspase1 (CASP1), Perforin 1 (PRF1) and Chemokine receptor CXCR3 (CXCR3)." (PMID 34503273, 2021). "A slight increase of IFI27, FOXQ1, PRF1, and SLC2A3 genes in CSCs probably implicate in phenotypes of cancer stem cells that were often quiescent, but being able to exhibit their chemoresistant properties." (PMID 32592372, 2020). "Additionally, we collected the IC50 values of drugs from various cancers and cell lines from the GDSC and CTRP databases in order to correlate them with GZMA, GZMB, GZMK and PRF1 expression levels." (PMID 40002821, 2025). "In addition, our current understanding of the complete roles of GZMA, GZMB, GZMK and PRF1 are still evolving and other factors may play a role in the varying expression levels of these genes in the context of the different clinical prognoses seen in these cancer types." (PMID 40002821, 2025). "Finally, PRF1 displayed the greatest activating effects on the Apoptosis pathway (56%), followed by the EMT (31%) and Hormone ER (28%) pathways in cancer." (PMID 40002821, 2025). "Intratumoral immune cytolytic activity (CYT), calculated as the geometric mean of granzyme-A (GZMA) and perforin-1 (PRF1) expression, has emerged as a critical factor in cancer immunotherapy, with significant implications for patient prognosis and treatment outcomes." (PMID 38612436, 2024). "Our findings revealed a positive correlation between the expression levels of LAG3 and IFNG (R = 0.76, p < 0.001), PRF1 (R = 0.75, p < 0.001), FASLG (R = 0.75, p < 0.001), GZMH (R = 0.74, p < 0.001), NKG7 (R = 0.74, p < 0.001), and PDCD1 (R = 0.73, P < 0 0.001) in pan-cancer tissues." (PMID 38115039, 2023). "The cytolytic activity (CYT) score is a new index of cancer immunity calculated from the mRNA expression levels of GZMA and PRF1; we concluded that the HCC patients with higher ICRPI had lower CYT scores compared to those observed in lower ICRPI patients (p < 0.01)." (PMID 36611994, 2023). "More importantly, the expression of PIK3R4 in DLBCL was correlated with the immune cell content in the cancer microenvironment, CD8(+) T-cell and neutrophil infiltration and the levels of several immune checkpoint molecules, including BTN3A2, BTN3A1, PRF1, CXCL9, PDCD1, and TIGIT." (PMID 37670973, 2023).
cancer (continued). "We first explored whether RE neoantigen burden might be associated with somatic neoantigen burden, expression of the immune markers including GZMA/PRF1/PD1, cytolitic activity (CYT), and clinical covariates in different cancer types." (PMID 33363023, 2020). "Finally, we found that IDO1 and the cytotoxic molecules including PRF1 and GZMA had a positive correlation with the PD-1 in most cancer types." (PMID 30607140, 2018). "CTL/NK cells can kill cancer cells by overexpressing GZMA and PRF1." (PMID 29515971, 2018). "Interestingly, CD4+ Texterm phenotype exhibited the highest expression of cytotoxic markers (PRF1, GZMA, GZMB, IFNG, and GNLY), aligning with recent discoveries indicating that cytotoxic CD4+ T cells within tumors can directly kill cancer cells." (PMID 40335494, 2025). "Notably, the GZMA CD4 T cell subset exhibited elevated expression of genes associated with effector and cytolytic functions in CD4 T cells, including GZMA, GZMH, GZMM, and PRDM1, while also showing moderate expression of anti-cancer-related genes such as IFNG, PRF1, and TNFSF10." (PMID 40959273, 2025). "Interestingly, the expression levels of the cytotoxic effectors PRF1, GNLY, GZMA, GZMB and GZMH in CD8+ Tex subclusters were even richer than those in CD8+ Teff subclusters, which implied that CD8+ Tex cells still tended to respond to cancer cells." (PMID 35562760, 2022). "Moreover, Granzyme A (GZMA) and Perforin 1 (PRF1), which have been validated as surrogates of immune activity in cancer, were not expressed in either dataset." (PMID 31383035, 2019). "However, responders had an increase in CD8, GZMA and PRF1 expression levels compared to non-responders, implying that cytolytic T lymphocytes with high cytotoxic activity were strongly infiltrated, expanded, and activated in cancer tissues by dual blockade in responders and TNBC patients." (PMID 29721177, 2018).
infection (52 papers, 2008 to 2025). The state of being infected such as from the introduction of a foreign agent such as serum, vaccine, antigenic substance or organism. "The M2 infection module revealed Chil3, Il4, Cx3cr1, Emr1 and Ccl2 as hubs, while module M6, associated with vaccination, disclosed Prf1, Klrc1, IFN-γ, Ncr1 and Tbx21 as hub proteins." (PMID 39563428, 2024). "For all infection experiments there was an upregulation of genes associated with cytotoxic cells, mainly granzyme A and B, perforin 1 and NKG2D." (PMID 24340121, 2013). "Although undiagnosed hypomorphic genetic variants in genes such as PRF1 or UNC13D remain a theoretical predisposition, the patient’s rapid response to therapy strongly supports a predominant, infection-driven secondary etiology." (PMID 41357205, 2025). "In contrast, Class1 was dominated by viral-infection annotations and antigen presentation (e.g., HLA-DRB1/DQB1/C, CD74, CTLA4, GZMB, PRF1), consistent with HIV-associated immune activation." (PMID 41394852, 2025). "The results showed that most pro-inflammatory markers, such as granzyme, Lamp1, Ifng, Prf1, Ccl5, Emoes, and Id2 transcription, increased after infection." (PMID 41459157, 2025). "In the macaque model of TB, CD8+ T cells expressing PRF1, GZMB, and GNLY were associated with protective granuloma and linked with protection from Mtb in the early stage of infection." (PMID 39836471, 2025). "This study revealed that the deletion of UeMsb2 significantly reduced the expression of b signaling pathway genes, including Prf1, Hdp1, Rbf1, Biz1, Clp1, and Kpp6, during hyphal growth and infection in U. esculenta." (PMID 39728314, 2024). "Although 45% of sugarcane seedlings induced by ssccp1Δ/con-PRF1 mutant to form black whip were lower than those of the wild type, infection was significantly higher than for the infection with the ssccp1Δ mutant." (PMID 37819114, 2023). "The expression levels of Gzma, Gzmb, Gzmk, and Prf1 were markedly lower at 6 weeks than at 4 weeks post infection, suggesting that NK cell function was inhibited from 6 to 8 weeks post infection." (PMID 36930687, 2023). "In our previous study, the expression of IFN-γ, Prf1, and Gzmb in NK cells increased between 2 and 4 weeks post infection and decreased between 6 and 10 weeks post infection." (PMID 36930687, 2023). "Herein, we show that ruxolitinib is well-tolerated and lessens disease features following infection of Prf1−/− mice with two different viral strains, LCMV Armstrong and LCMV WE." (PMID 37228616, 2023). "Patients with COVID-19 infection have higher levels of GZMs and PRF1 than healthy controls; they also have characteristic expression changes during infection recovery." (PMID 36437952, 2022). "Immune cells during infection remain active by increased expression of PRF1 and granzymes, despite the reduction in the total number of cells." (PMID 34945761, 2021). "On the contrary, Prf1 mRNA expression decreased significantly in the 1st week post infection (p < 0.01) and increased significantly at other time points (p < 0.01)." (PMID 34421855, 2021). "Further, comparative analysis of animals with different severity to infection highlights the potential importance of genes such as perforin-1, ENPP2 and CCL20 in conferring higher resistance against AGD." (PMID 30873203, 2019). "The proportion of Prf1−/−Il1rl1−/− cells within the gp33-specific subset was also markedly reduced relative to Prf1−/− cells after infection, despite similar baseline ratios of Prf1−/− to Prf1−/−Il1rl1−/− CD8+ T cells in uninfected mixed BM chimeras." (PMID 30515155, 2018). "Fourthly, naïve NK cells that were transferred from intact C57BL/6 mice into T. brucei–infected Prf1-/- mice prevented infection-induced expansion of splenic B2 B cells consistent with in vivo B cell depletion." (PMID 27403737, 2016).
infection (continued). "Several strains of mutant C57BL/6 mice (TCR-/-, C3-/-, CD16-/-, MyD88-/-, TRIF-/-, INFγ-/-, TNFR1-/-, Gal3-/-, Prf1-/-) with defects in innate and adaptive immunity were examined for expression of this infection-induced, immunosuppressive trait." (PMID 27403737, 2016). "At day 6 after infection, Prf1 KO mice were pancytopenic affecting leukocytes, lymphocytes, and platelets." (PMID 22891066, 2012). "Although the proportion of CD8+ CTLs decreased from 5.48% to 4.13% after infection, these cells exhibited enhanced expression of cytolytic genes (nkl, gzmb, gzma, and prf1) and chemokines (ccl5l, ccl20, mcp1b, and ccl4l), while decreased the expression of il34." (PMID 40821846, 2025). "Additionally, we observed the significant downregulation of PRF1 gene expression following infection." (PMID 39650642, 2024). "Consistently, the relative fungal biomass was significantly reduced at 3 days post infection (dpi) with ssccp1Δ and ssccp1Δ/con-PRF1 mutants, compared to the wild-type and genetic complementary strain combinations, suggesting that SsCcp1 is instrumental in ROS detoxification." (PMID 37819114, 2023). "Transcriptome sequencing in the present study revealed that the expression levels of Ifn-γ, Prf1, and Gzmb were significantly lower 6 weeks post infection than 4 weeks post infection, indicating that NK cells were in an inhibited state at 6 weeks post infection." (PMID 36930687, 2023). "Importantly, lung gene transcript expression was consistent with the cellular phenotype and functional data, with T cell responses including TBET, IFNG, GZMB, and PRF1 upregulation throughout infection." (PMID 36146518, 2022). "Thus, the reduced Th1 responses and expression of IFNG, TNF, GZMB, and PRF1 in CD4+ Trms may indicate the impaired anti-infection capacity in COPD airways." (PMID 40589761, 2025). "Finally, immune factors prevent pathogenic infection in vertebrate gestational tissues, and our dataset identifies several candidate genes responsible for immune defence in the pregnant dunnart uterus (BPI, BPIFB1, GZMA and PRF1)." (PMID 29402916, 2018). "Importantly, double cytokine-deficient mice did not display enhanced GzmB nor Prf1 protein levels following infection." (PMID 26720279, 2015). "To investigate if the other CXCR3 ligand, CXCL10, or the receptor itself are contributing to murine FHL, we treated prf1−/− mice infected with LCMV to induce FHL with a CXCR3 antagonist, AMG487, starting at day 3 post infection (p.i)." (PMID 37516815, 2023). "Flow cytometry and RT-qPCR showed that the levels of effector molecules in hepatic NK cells, such as IFN-γ, Prf1, Gzmb, IL-10, and TNF-α, were higher in Tigit-/- mice than in WT mice at 4 and 6 weeks post infection." (PMID 36930687, 2023). "The expression of Perforin (Prf1) and Granzyme B (Gzmb) in the spleen TIGIT+ T cells of mice infected with PRU cysts was significantly upregulated at the 1st week post infection (p < 0.01)." (PMID 34421855, 2021). "Ultimately, the upregulation of effector molecules, such as cytokine TNF, cytolytic molecule perforin (PRF1), and adhesion molecule ICAM1, enhance the protection against infection, killing of bacterial-infected cells, and cell migration to infected tissues." (PMID 32582206, 2020). "In up-regulated genes of head kidney samples, 2 genes respond to infection by D. pseudospathaceum-clone I (HYAL2, PRF1), 3 to clone XII (RGCC, CYP27B1, CCR9) and 6 to the clone mix treatment (ITGA5, SIX1, ATP1B3, MEF2C, MLF1, MYLPF)." (PMID 25254967, 2014). "Prf1 KO and BL/6 WT control mice were infected with MCMV and treated with 10 μg of IL-18BP or vehicle starting 84 h after infection." (PMID 22891066, 2012). "In Prf1 KO mice, HLH is triggered by MCMV infection but as viral replication increases rapidly, the infection becomes lethal." (PMID 22891066, 2012). "Prf1 KO mice were infected with 1 × 106 PFU of in vitro-derived DN-SCP-MCMV and starting 84 h after infection, mice received DOX, IL-18BP, or a combination of both." (PMID 22891066, 2012).
infection (continued). "Indeed, challenge infection with Tc led to significant expansion of effector CD4+ and CD8+ T cells and production of cytotoxic molecules (IFNγ, PRF1, GZB) by both CD4+ and CD8+ effector T-cell subsets in vaccinated (vs. non-vaccinated) pregnant mice." (PMID 38104118, 2023). "PRF1, GZMB, and GNLY genes expressed at the fifth day of infection were upregulated." (PMID 34945761, 2021). "Trypanosoma brucei AnTat 1.1-infected Prf1-/- mice that did not develop ruffled fur were subjected to autopsy at 90 days post infection." (PMID 27403737, 2016). "Infected Prf1-/- mice mounted higher-titer IgM, IgG, IgG1 and IgG2a antibody responses against T. brucei AnTat 1.1 components present in 0.5% NP40 lysate than infected intact mice during the first 30 days after infection, as shown by ELISA." (PMID 27403737, 2016). "When inoculated with 1.5 × 104 PFU of MCMV, BL/6 WT mice normally survived infection, showing no sign of illness, however Prf1 KO mice died between day 6 and day 13 after infection." (PMID 22891066, 2012). "A slightly lower frequency of CD8+ T cells in Prf1−/− mice was observed, regardless of infection." (PMID 27092144, 2016). "In addition, T cell receptor beta chain (Tcrb)−/−→ Sod1−/− and perforin 1 (Prf1)−/−→ Sod1−/− bone marrow chimeric mice, lacking either αβ T cells or the hematopoietically-expressed cytolytic effector protein PRF1 respectively, exhibited liver damage similar to controls upon infection." (PMID 26588782, 2015). "Unlike uninfected NK cells, uninfected blood CD8+ T cells did not express Prf1 or Gzma, suggesting that cytotoxic gene expression in CD8+ T cells was infection-induced." (PMID 39749347, 2024). "However, splenic B2 B cell numbers were significantly decreased at day 10 after infection relative to those in infected mice injected iv with PBS, but not relative to uninfected Prf1-/- mice." (PMID 27403737, 2016).